ACAP1 (ArfGAP with coiled-coil, ankyrin repeat and PH domains 1)
Description:
GTPase-activating protein (GAP) for ADP ribosylation factor 6 (ARF6) required for clathrin-dependent export of proteins from recycling endosomes to trans-Golgi network and cell surface. Required for regulated export of ITGB1 from recycling endosomes to the cell surface and ITGB1-dependent cell migration.
Synonyms: CENTB1; KIAA0050
Tractability: Antibody: UniProt places it where antibodies can reach, with high confidence. PROTAC: ubiquitination databases record sites on it; its protein half-life has been measured.
Gene: Protein-coding gene on chromosome 17 (7,332,960 to 7,351,478, forward strand). Ensembl gene ENSG00000072818.
Subcellular location: Recycling endosome membrane
Subcellular location (Human Protein Atlas): Golgi apparatus
Gene Ontology:
Molecular function: protein binding; GTPase activator activity
Biological process: actin cytoskeleton organization
Cellular component: membrane; endosome membrane; cytoplasm; recycling endosome membrane
Genetic constraint (gnomAD): Loss-of-function variants: 45 observed, 99.6 expected, observed/expected ratio (o/e) 0.45, 90% interval 0.35 to 0.58. The upper end of that interval is the gene's LOEUF score, 0.58, which puts it in group 2 of 6, group 1 being the genes least tolerant of losing a copy. Missense variants: 735 observed, 988.95 expected, observed/expected ratio (o/e) 0.74, 90% interval 0.7 to 0.79. Synonymous variants: 362 observed, 378.88 expected, observed/expected ratio (o/e) 0.96, 90% interval 0.88 to 1.04.
Homologues: Orthologues: chimpanzee ACAP1 (99% identical), macaque ACAP1 (98% identical), rabbit ACAP1 (96% identical), pig ACAP1 (95% identical), guinea pig ACAP1 (94% identical), mouse Acap1 (93% identical), dog ACAP1 (92% identical), rat Acap1 (92% identical), tropical clawed frog acap1 (59% identical), zebrafish acap1 (59% identical). Paralogues in human: ACAP2 (54% identical), ACAP3 (53% identical), ASAP2 (24% identical), ASAP3 (22% identical), ASAP1 (22% identical), AGAP3 (21% identical), AGAP1 (20% identical), AGAP2 (19% identical), ARAP1 (19% identical), ARAP2 (18% identical), ARAP3 (16% identical), AGAP4 (16% identical), and 16 more.
Diseases named in the same sentence as ACAP1 in open-access papers:
ACAP1 is named in the same sentence as 18 diseases in open-access papers, as found by Europe PMC text mining. Sharing a sentence is not in itself a finding about the gene and the disease. The quoted sentences say what the papers report.
breast carcinoma (6 papers, 2017 to 2022). "Most noteworthy was rs35776863, which not only had the strongest association with breast cancer risk (p-value: 1.4x10-04), but also contributed nearly half of the weight for predicting ACAP1 expression (49%)." (PMID 28362817, 2017). "Among the 19 ACAP1 whole blood eQTL SNPs, five were nominally associated with breast cancer risk." (PMID 28362817, 2017). "The amounts of ACAP1 are higher in highly invasive breast cancer cell lines than in weakly invasive or noninvasive cell lines." (PMID 32503630, 2020). "The protein level of ACAP1 was significantly lower than normal tissues in three cancer types, including breast cancer, colon cancer, and LIHC but significantly higher than corresponding normal tissues in four cancer types, including ccRCC, HNSC, PAAD, and UCEC." (PMID 36497434, 2022). "ACAP1 is involved in cell membrane transport and cell migration, is an Arf6 GAP, that is, important for immune cell migration and infiltration, and is associated with tumor immune infiltration and prognosis in breast cancer." (PMID 35432443, 2022). "We also found some support for an association between breast cancer risk and eQTL for ACAP1 (EUGENE P = 0.003) and ANKLE1 (EUGENE P = 0.01), but not for DHODH (best sentinel eQTL P = 0.119)." (PMID 30988301, 2019). "Furthermore, we found that higher expression levels of ACAP1 (p-value: 1.9x10-05) and LRRC25 (p-value: 5.2x10-05) were suggestively associated with an increased risk of breast cancer." (PMID 28362817, 2017). "ACAP1 (i.e., ArfGAP with coiled-coil, ankyrin repeat and PH domains 1) has not been implicated in breast cancer risk, but it has been shown to potentially play a role in disease progression." (PMID 28362817, 2017). "SLC2A4 encodes a protein that functions as an insulin-regulated facilitative glucose transporter; inhibition of this gene affects cell proliferation and cell viability, suggesting a potential biological hypothesis for how ACAP1 may be involved with breast cancer." (PMID 28362817, 2017). "Neither ACAP1 nor LRRC25 have previously been implicated by GWAS of breast cancer risk." (PMID 28362817, 2017).
colon cancer (2 papers, 2021 to 2022). "In addition, colon cancer-related genes were also involved in the co-occurrence with RP11-284N8.3 (P = 1.1E10-6 for ACAP1 and P = 3.09E10-5 for COLCA2)." (PMID 34131286, 2021).
glioma (2 papers, 2020 to 2022). A benign or malignant brain and spinal cord tumor that arises from glial cells (astrocytes, oligodendrocytes, ependymal cells). "As a key transport effector in the recycling of integrin β1, the inhibition of ACAP1 activation would lead to the suppression of glioma cell invasion." (PMID 32503630, 2020).
gastric cancer (1 paper, 2022). A primary or metastatic malignant neoplasm involving the stomach. "ACAP1 exhibited a modest predictive performance and was comparable to other biomarkers in gastric cancer, ccRCC, glioblastoma, and mUC (metastatic urothelial cancer)." (PMID 36497434, 2022).
lung carcinoma (1 paper, 2022). "Further, analysis from two lung cancer cohorts (“Ruppin 2021” for LUAD and GSE126044 for NSCLC) revealed that low ACAP1 expression was significantly associated with decreased response rate and worse OS/PFS in patients treated with anti-PD-1 antibodies." (PMID 36497434, 2022). "Notably, ACAP1 exhibited good power in predicting ICT response in lung cancer (AUC = 0.8286, “Ruppin 2021” cohort), pronouncedly superior to other biomarkers." (PMID 36497434, 2022). "Consequently, the low expression of ACAP1 indicated resistance to immunotherapy and was associated with poor outcomes in multiple cancer patients following ICT, especially in patients with melanoma or lung cancer." (PMID 36497434, 2022).
lymphoma (1 paper, 2022). A malignant (clonal) proliferation of B- lymphocytes or T- lymphocytes which involves the lymph nodes, bone marrow and/or extranodal sites. "Analysis from three different SPI1 ChIP-seq datasets, including GSM1681425 in macrophage, GSM1703900 in B lymphocyte, and GSM1480737 in lymphoma, demonstrated that SPI1 binds to the ACAP1 promoter." (PMID 36497434, 2022).
melanoma (1 paper, 2022). A malignant, usually aggressive tumor composed of atypical, neoplastic melanocytes. "Analysis from the “Gide 2019” cohort revealed that low ACAP1 levels were also associated with inferior response, OS, and PFS in melanoma patients treated with anti-PD-1 alone or in combination with anti-CTLA-4 antibodies." (PMID 36497434, 2022). "Analysis from the “Riaz 2017” cohort showed that low ACAP1 levels were associated with worse response and OS in melanoma patients treated with anti-PD-1 antibodies regardless of whether the samples were collected prior to or during therapy." (PMID 36497434, 2022). "Analysis of two melanoma single-cell sequencing cohorts, including GSE72056 and GSE115978, revealed that ACAP1 was highly expressed in lymphocyte cells, including T, B, and NK cells but was barely expressed in malignant cells and other types of immune cells." (PMID 36497434, 2022). "Analysis from “VanAllen 2015” and “Snyder 2014” cohorts showed that ACAP1 expression in the non-response group was lower than in the response group of melanoma patients receiving anti-CTLA-4 therapy." (PMID 36497434, 2022). "The prediction performances of ACAP1 were better than TIDE, MSI, TMB, and CD274 in >50% of melanoma cohorts and achieved a high prediction accuracy of ICT response with an AUC > 0.7, predicting a strong likelihood of positive response to immunotherapy, in four cohorts." (PMID 36497434, 2022). "In addition, ACAP1 expression does not highly correlate with TMB in the majority of tumors, such as melanoma, which has the highest TMB." (PMID 36497434, 2022).
tumor (6 papers, 2019 to 2025). "Overall, these results indicate that, despite the prognostic significance of ACAP1 expression varied by tumor type, low ACAP1 expression was associated with poor clinical outcomes in the majority of tumor types, especially solid tumors." (PMID 36497434, 2022). "In some published studies, ACAP1 was found to be associated with tumor purity and CD8+ T cell toxicity in BCLA basal squamous subtype and luminal infiltrated subtypes." (PMID 34112144, 2021). "The result indicated that loss of ACAP1 impaired the cytotoxicity of lymphocytes to tumor cells." (PMID 36497434, 2022). "Therefore, we speculate that ACAP1 is also necessary for the activation and function of these cells and that the loss of ACAP1 in lymphocytes would impair their ability to kill tumor cells, leading to poor immunotherapy outcomes." (PMID 36497434, 2022). "ACAP1 levels positively correlate with the infiltrating levels of tumor-infiltrating lymphocytes (TILs) across a broad range of solid cancer types." (PMID 36497434, 2022). "We then profiled the expression of ACAP1 in tumor samples and corresponding normal samples across 33 TCGA cancer types by integrating the sequencing data from the TCGA and GTEx datasets." (PMID 36497434, 2022). "Functionally, the depletion of ACAP1 by RNA interference significantly impairs the T cell-mediated killing of tumor cells." (PMID 36497434, 2022). "There was also an inverse correlation between ACAP1 expression and the β value of these CpG sites in a variety of tumor types, especially cg25671438 site." (PMID 36497434, 2022). "In this study, we demonstrated that ACAP1 expression is required for the cytotoxicity of T cells to tumor cells." (PMID 36497434, 2022). "Pairwise comparisons between tumor and tumor-adjacent samples in the TCGA cohorts showed that ACAP1 expression was significantly lower in eight cancer types (BLCA, BRCA, COAD, KICH, LUSC, PRAD, THCA, and UCEC) but higher in four cancer types (CHOL, HNSC, KIRC, and STAD)." (PMID 36497434, 2022). "Moreover, single-cell sequencing analysis in tumor samples revealed that ACAP1 is expressed primarily in tumor-infiltrating lymphocytes (TILs), including T, B, and NK cells." (PMID 36497434, 2022). "As ACAP1 expression was strongly correlated with immune cytotoxicity activity and the infiltrating level of CD8+ T cells in tumors at a pan-cancer level, we wondered whether ACAP1 expression could predict the tumor response to ICT and the prognosis of ICT-treated patients." (PMID 36497434, 2022). "Therefore, we speculate that lymphocytes with high expression levels of ACAP1 are more likely to infiltrate into tumors, thus killing tumor cells more effectively." (PMID 36497434, 2022). "We found ACAP1, IFIT3 and TAP1 were upregulated in tumor samples, while ADAMTS9, COL6A2, FBN1 and FSTL1 were downregulated in tumor specimens." (PMID 34112144, 2021). "CD48, SEPT1, ACAP1, PPP1R16B, and IL16 were all negatively correlated with tumor purity, supporting the results for highly correlating with ICILs." (PMID 31737562, 2019). "Interestingly, hypoxia, an important tumor microenvironmental stimulus, increased the expression of both SPI1 and ACAP1 in Jurkat cells." (PMID 36497434, 2022). "Additionally, when DEA was performed between tumor and normal tissues from the validation set, it could be seen that both genes were highly expressed in tumor tissues, but RASGRP1 was a differentially expressed gene, while ACAP1 was not." (PMID 32503630, 2020).
cancer (4 papers, 2020 to 2025). A tumor composed of atypical neoplastic, often pleomorphic cells that invade other tissues. "Moreover, ACAP1 deficiency is associated with poor prognosis and immunotherapeutic response in multiple cancer types treated with immunotherapy." (PMID 36497434, 2022). "It revealed that the low expression of ACAP1 tended to be accompanied by advanced stages in most cancer types." (PMID 36497434, 2022). "The expression of ACAP1 (ArfGAP with coiled-coil, ankyrin repeat and PH domains 1) is correlated with immune infiltration levels in many types of cancers." (PMID 35800363, 2022). "Spearman correlation analyses in TCGA cohorts indicated that ACAP1 expression was significantly positively correlated with its copy number in 23 types of cancer, suggesting that it was at least partially regulated by CNV in these tumors." (PMID 36497434, 2022). "Altogether, the ACAP1 expression in cancers was lower than in normal or paracancerous tissues in the majority of cancer types, although the differential expression between them varies across cancer types." (PMID 36497434, 2022). "Conversely, ACAP1 expression was significantly increased in six cancer types: CHOL, HNSC, KIRC, KIRP, LAML, and PAAD, compared to normal samples." (PMID 36497434, 2022). "To identify the specific pathways associated with ACAP1 expression, we initially performed pathway enrichment analysis using GSEA for each TCGA cancer type based on ACAP1 expression in TCGA cohorts." (PMID 36497434, 2022). "Pan-cancer expression analysis of ACAP1 showed that ACAP1 was significantly decreased in most cancer types but significantly increased in several cancer types, such as CHOL, HNSC, and KIRC." (PMID 36497434, 2022). "We next evaluated the prognostic value of ACAP1 mRNA expression for cancer patients by Kaplan–Meier analysis of OS (overall survival), DSS (disease-specific survival), and PFI (progression-free interval)." (PMID 36497434, 2022). "We found that cg25671438 was hypomethylated in three immune-related cancer types (DLBC, LAML, and THYM) with a high expression level of ACAP1, while it was hypermethylated in other cancer types that possessed a low ACAP1 expression level." (PMID 36497434, 2022). "Spearman correlation analysis revealed that ACAP1 expression was significantly negatively correlated with the average methylation level of the ACAP1 promoter in 29 cancer types of TCGA." (PMID 36497434, 2022). "Consistently, analysis of ACAP1 expression in cancer cell lines from the “Cancer Cell Line Encyclopedia” showed that its expression was high in hematopoietic and lymphoid cell lines but barely expressed in other cell lines." (PMID 36497434, 2022). "This work systematically explores the genetic alterations, expression patterns, prognostic significance, and transcriptional regulation of ACAP1 across various cancer types." (PMID 36497434, 2022). "Functions of ACAP1 in mediating endocytic recycling and cell migration have been investigated already, but there is limited information on human cancers." (PMID 32503630, 2020). "The quantitation of ACAP1 expression could help determine appropriate therapies for cancer patients, although many preclinical studies need to be done before clinical application." (PMID 36497434, 2022). "To determine whether ACAP1 expression reflects cancer progression, we assessed ACAP1 expression in different T, N, M, and pathologic stages." (PMID 36497434, 2022). "Moreover, we found that ACAP1 expression was strongly positively correlated with cytotoxicity score (CYT) and the expression of GZMA and PRF1, which encode two key cytolytic effectors (granzyme A and perforin 1), in most cancer types." (PMID 36497434, 2022). "All of these immune deconvolution analyses showed that ACAP1 was significantly positively correlated with the level of CD8+ and CD4+ T cells in most cancer types, except DLBC." (PMID 36497434, 2022).
cancer (continued). "ACAP1 deep deletion and amplification, both of which are CNV, were observed in most cancer types (25 of 32)." (PMID 36497434, 2022). "Spearman correlation analysis indicated a strong positive correlation between ACAP1 and SPI1 expression in the TCGA pan-cancer dataset and 28 types of cancer from TCGA." (PMID 36497434, 2022). "Thus, the analyses of immune infiltrates from different methods consistently pinpointed that ACAP1 expression was significantly positively correlated with the level of TILs, especially CD8+ T cells, in the majority of cancer types." (PMID 36497434, 2022).
infection (3 papers, 2015 to 2019). The state of being infected such as from the introduction of a foreign agent such as serum, vaccine, antigenic substance or organism. "Interestingly, SH3BP4 and ACAP1, which have been shown to promote TfnR endocytosis and recycling by binding to the receptor, were also recruited to infection sites in a T3SS-dependent manner." (PMID 31242273, 2019). "Further, a number of these CIE regulators, including Rab11a, Hook1, ACAP1/2, and EHD3, are targeted by microRNAs or downregulated by infection with HCMV." (PMID 30042195, 2018). "To determine the influence of ACAP1, ADAP1, and ASAP1 on Salmonella remodeling of the cytoskeleton, we examined Salmonella invasion after a 15-min infection of Caco cells individually expressing recombinant hemagglutinin (HA)-tagged Arf GAPs." (PMID 25670778, 2015).
gynecologic tumors (1 paper, 2022). "ACAP1 is closely bound up with the level of immunocyte infiltration, immune regulators and chemokines, and has been used in the prediction of clinical outcomes with several tumors, including gynecologic tumors." (PMID 35884444, 2022).
hematological malignancies (1 paper, 2022). "Interestingly, a trend towards better OS was observed in hematological malignancies (DLBC and LAML) in patients expressing low ACAP1 expression." (PMID 36497434, 2022).
ACAP1 also shares sentences with these, for which no sentence is quoted: bladder cancer (1 paper); esophageal cancer (1); glioblastoma (1); hypothyroidism (1); kidney cancer (1); liver cancer (1).